AR (androgen receptor)
Diseases named in the same sentence as AR in open-access papers (continued):
Sharing a sentence is not in itself a finding about the gene and the disease.
tumor (continued). "Since tumors are very heterogeneous; it is probable that in some tumors, high expression of AR may stimulate the expression of DNA repair-related genes including DDB2 and in these cases tumor cells may have developed other strategies to antagonize DDB2." (PMID 28212551, 2017). "Regarding clinical and pathologic features, the study established a correlation with AR positivity and smaller tumor size (<2 cm), absence of lymph node metastases and PR expression." (PMID 28245550, 2017). "While single pathway inhibition with either enzalutamide or BEZ235 (a PI3K inhibitor) only had modest cytostatic effects, the combination of AR and PI3K pathway inhibition (in particular PI3K and/or mTORC 1/2) or PI3K inhibition and HER2/3 inhibition led to significant tumor reductions." (PMID 28420128, 2017). "Response to androgen deprivation therapy in mice with CWR22RV1 xenografts, suggests that AR may regulate HIF-1α levels, as expression of both AR and HIF-1α target genes were affected even outside of hypoxic tumor areas." (PMID 28394264, 2017). "Using a cutoff value of 20% nuclear staining of tumor cells, we found that AR-negative patients had a significantly worse prognosis than AR-positive patients, although the ERβ expression did not influence the survival." (PMID 28938615, 2017). "The study that reported AR predicting better DFS in ERα-positive tumor showed no impact on survival of TNBC by AR, but having trends of poorer outcome in the ERα-negative with HER2-positive status only." (PMID 28474005, 2017). "A recent study showed that the AR antagonist enzalutamide, which directly binds the ligand binding domain of AR with higher affinity than dihydrotestosterone (DHT), inhibited PT12 patient-derived xenograft (PDX) tumor growth." (PMID 29254284, 2017). "Nonetheless, these immunohistochemical studies have failed to reveal significant sex-related differences in AR expression in male versus female tissues (normal, tumor)." (PMID 28241422, 2017). "We also reported that the AR/FOXA1 response gene FOXP1 acts as a negative AR collaborative transcriptional factor, and represses tumor activity by binding to adjacent regions to AREs." (PMID 28264478, 2017). "The majority of ccRCCs (61%, 290/477) showed no AR expression or only in a small subpopulation of tumor cells (0 to 5%)." (PMID 29108248, 2017). "Upon emergence of CRPC, both AR and PSA were dramatically overexpressed in the LuCaP 35CR tumor." (PMID 28886115, 2017). "This enriched binding at the GR locus, together with the primary transcriptional effects on GR and not AR targets, suggests that the anti-tumor activity of JQ1+Enz in the LREX’ xenograft model is most likely through GR inhibition." (PMID 28891793, 2017). "In vivo study showed that Wedelia chinensis extract inhibited the function of androgen receptor (AR) signaling and the tumor growth of AR-positive PCa without adverse toxicity as observed by body weight and physical activities." (PMID 29142311, 2017). "The major mechanism of resistance to castration is an acquired capability that allows CRPC to survive under the surroundings without sufficient DHT for AR activation and tumor progression." (PMID 28287091, 2017). "The difference in AR expression in tumor with GU weight > 1 gram was not statistically significant between treatment and control, as previously reported." (PMID 28765837, 2017). "Interestingly, thymoquinone inhibited the tumor growth of CRPC xenografts and repressed E2F-1 and AR expression." (PMID 28264478, 2017).
tumor (continued). "A statistical analysis of clinical factors demonstrated that advanced disease stage, tumor diameter ≥2 cm, positive axillary lymph node metastasis, higher histological grade, and negative tumor AR expression correlated significantly with poorer RFS." (PMID 28067809, 2017). "Bilateralism of the tumours, presence of Reinke crystals and expressions of synaptophysin, Inhibin α, CD56, androgen receptor, DLK1, INSL3, CYP11B1, CYP21A2 and MC2R have all been studied as potential markers, but none of these markers individually can reliably discriminate TARTs from LCTs." (PMID 29038332, 2017). "Our data also suggest that in the absence of ID4, FKBP52 significantly potentiated AR signaling leading to increased proliferation and tumor growth." (PMID 28252832, 2017). "However, some tumours will become hormone refractory following ADT, featured by increasing PSA levels in blood and upregulation of the AR in cancer cells." (PMID 28241429, 2017). "Meanwhile, icaritin is able to target androgen receptor and androgen receptor COOH-terminal truncated splice variants, to inhibit androgen receptor signaling and tumor growth with no apparent toxicity." (PMID 28785509, 2017). "In ER positive tumours that respond to neoadjuvant endocrine therapy, AR mRNA and protein expression decreases, whereas in tumours those fail to respond, AR mRNA does not decrease." (PMID 28733469, 2017). "More recently, non-genomic actions of the AR signaling pathway have been described and are still being investigated in both normal female tissue and in tumor carcinogenesis." (PMID 28245550, 2017). "PSA transcription is predominantly regulated by the AR and therefore, serum PSA levels could be regarded as a surrogate marker of AR activity in tumor cells." (PMID 28604629, 2017). "Cox multivariate analysis confirmed the lack of AR tumor expression in primary ovarian lesions as a negative independent prognostic parameter, supporting brain metastasis progression (p=0.053, CI 95% 1.000-1.073)." (PMID 28467804, 2017). "Survival duration from tumor biopsy was also affected by AR expression, but without statistical significance (p=.102)." (PMID 28060723, 2017). "Thus, our results indicate that, along with reduced castration-resistant tumor formation, TRX1 suppression produces elevated AR levels under systemic AD in vivo." (PMID 29089489, 2017). "Src was shown to enhance the tumor progressive properties of AR in the absence of specific ligands to activate AR." (PMID 28671964, 2017). "Cumulative evidences showed that enzalutamide has potent anti-tumor effects on TNBC cells, and suggested that androgen receptor (AR) might be a promising target for treatment of TNBC." (PMID 29261702, 2017). "More importantly, this biologic mechanism explains how PCa adapts to ADT and why available AR antagonists do not have substantial activity against the castrate resistant tumor cells emerging after ADT." (PMID 29262604, 2017). "Their hypothesis that ADT interferes with NHEJ originated from their data that showed that AR interacts with Ku70, a protein that binds DSBs and initiates NHEJ, in PCa tumor tissue." (PMID 27487144, 2016). "These patients with AR-positive tumor included 22% of male responders vs. 46% of male non-responders and 20% of female responders vs. 40% of female non-responders." (PMID 27322140, 2016). "In the present study, the effect of exosomes derived from androgen receptor (AR) positive or negative PCa cell derived exosomes on PCa tumour growth, progression and survival properties was investigated." (PMID 26840259, 2016). "The recent development of abiraterone acetate, which blocks the synthesis of androgens by the tumor, and the new high affinity anti-androgens, such as enzalutamide (formerly MDV3100), once again blocks AR action in CRPC validating that the AR pathway is a central target for drug therapy." (PMID 27542219, 2016).
tumor (continued). "In advanced PCa models, AR knockdown is very effective in repressing tumor growth, but this has not yet been achieved long-term in the clinic." (PMID 26657335, 2016). "In turn, increased AR expression leads to upregulation of the matrix metalloproteinases MMP1 and MMP13, mediators of extracellular collagen degradation with known roles in tumor invasion, metastasis, and BCa progression." (PMID 27437104, 2016). "However, after initial regress of the tumor in response to ADT, the disease relapses through the development of castration-resistance by adaptive responses of the AR." (PMID 27374083, 2016). "Of these four patients, three had tumors that were GR-positive/AR-negative, and one had a tumor which was AR-positive/GR-negative." (PMID 27386391, 2016). "In the absence of ER, AR instead binds androgen response elements and functions as an oncogene, promoting tumor growth via a separate pathway." (PMID 27285752, 2016). "Circulating tumor cells (CTC) that are NEPC show low or no AR expression (detected by IHC with the amino-terminal that would recognize all forms of the AR); therefore no proof exists if NEPC cells can express the ARVs." (PMID 27542219, 2016). "In the multivariable model, after adjusting for age, tumor grade and PD-L1, BRCA1 mutation status was no longer significantly associated with AR expression ⩾1 or >10%." (PMID 28721372, 2016). "Oral VT-464 or AA also stimulated increased expression of full-length AR and AR-V7, suggesting that both CYP17A1 inhibitors may activate similar tumor adaptation mechanisms." (PMID 27748439, 2016). "A new study has shown that 17/159 (10.7%) of CRPC patients have circulating tumor cells (CTCs) that are defined as NEPC since they have low or are absent for AR expression." (PMID 27542219, 2016). "In conclusion we have determined using a clinically relevant gene set that aggressive tumours have a deregulated AR transcriptome including expression of PSA and therefore aggressive, low-volume tumours may currently be overlooked by PSA screening." (PMID 27120785, 2016). "Tumour-derived gene expression data and cell line models imply that these tumours may benefit from alternative treatment strategies such as reprogramming the microenvironment and targeting the IGF and AR signalling pathways." (PMID 26943587, 2016). "In this study, we profile the expression pattern of AR in 450 patients, ranging from stage I to III based on Tumor, Node and Metastasis (TNM) staging system, and we correlated AR expression with clinical outcome to evaluate its prognostic implication alone or in combination with HR status." (PMID 27285752, 2016). "In addition, paired samples from primary and recurrent tumors from the same patient show that AR amplification, as measured by fluorescence in situ hybridization (FISH), occurs when the tumor transitions to a resistant state." (PMID 27487144, 2016). "We examined the expression of AR and Oct-4 genes in single side- and non-side population cells isolated from two non-tumor human prostate clinical specimens obtained from radical prostatectomy surgeries." (PMID 27785389, 2016). "Unlike PR, AR expression in metastatic lesions was significantly (P=0.039) higher than that in primary tumours." (PMID 26930451, 2016). "These evidences confirmed the lack of changes in AR status during hormonal treatment identified in circulating tumor DNA from 44 CRPC patients treated with abiraterone." (PMID 27191887, 2016). "In this light, AR was recently demonstrated to induce varied and distinct AR transcriptional programs in patient tumor tissue as opposed to PCa cell lines." (PMID 25744782, 2015).
tumor (continued). "The expression rates of AR, MMP-2 and MMP-9 in the HCC tissue were 76.67, 73.33 and 76.67%, respectively, all of which were significantly higher than those in the tissues adjacent to the tumor." (PMID 25667651, 2015). "Together, this study provided a preclinical proof-of-concept that combination of a PI3K/mTOR inhibitor with an AR inhibitor resulted in an anti-tumor activity in both non-CRPC and CRPC models." (PMID 26506516, 2015). "Interestingly, engineered overexpression of AR in immortalized PrEC induced a luminal cell phenotype with PSA expression, cell growth stimulated by androgens and formation of cribriform tumour nodules when implanted into the prostate of immunodeficient mice." (PMID 25864518, 2015). "In our experiment, AR is not active in the LNCaP model and the transcription abundance changes in both tumour and cell line data suggest that in at least the human data we compare with here, AR is not actively regulating its normal targets." (PMID 26553226, 2015). "Our study confirmed that lack of AR expression is a poor prognostic marker, since low AR expression correlated with a more aggressive tumor behavior and a poorer OS." (PMID 26039245, 2015). "This can especially be witnessed when pathologist-assigned scores are close to the cut-off values of calling a tumor positive or negative for any given marker and was the reason for the perceived discrepant AR status in 2/5 cases in this study." (PMID 26552477, 2015). "We noted that AR differed in expression across gender in the non-tumor compartment, but was not gender-specific in the tumor compartment." (PMID 26683690, 2015). "Androgens have also been shown to modulate the expression or activity of some molecules related to cell proliferation and/or tumor growth, such as β-catenin, CD24, epidermal growth factor receptor, and extracellular signal-regulated kinases (ERK), via the AR pathway." (PMID 26342199, 2015). "In the highly metastatic PC-3 cells which are also AR negative, NRs treatment also impaired cell migration and invasion, the late stage events essential for tumour metastasis." (PMID 25605250, 2015). "A half of mice injected with only 100 AR cells developed tumors, in contrast to no tumor with Br3CT cells, suggesting that AR tumors are enriched with tumor initiating cells." (PMID 26336988, 2015). "Therefore, in the second part of this project, we carried out exhaustive tumor-regeneration and serial transplantation studies in 2 AR+/PSA+ (LAPC9 and LAPC4) and 2 AR−/PSA− (PC3 and Du145) PCa models." (PMID 26246472, 2015). "This shows that tumour cells in CRPC can continue to survive, bypassing the AR signalling pathway." (PMID 26553226, 2015). "AR, MMP-2 and MMP-9 expression levels in HCC tissues have the potential to be employed as predictors of the progression of local cancer invasion and the tumor stage." (PMID 25667651, 2015). "AR represses MAD1L1, which functions as tumor suppressor to positively influence proliferation." (PMID 25781993, 2015). "Conversely in vivo knockdown of stromal AR was found to be more effective at inhibiting tumor growth in early stages of progression rather than at later stages." (PMID 25965833, 2015). "Conversely, since Gleason score in our cohort was found to be related to traditional tumor characteristics of poor prognosis, such as serum PSA, cancer-related death and epithelial AR content, the stromal AR results are likely reflective of what also happens in younger patients." (PMID 25965833, 2015). "Taken together, both in vitro and in vivo growth characteristics of PMEPA1shRNA harboring cells resulted in increased AR, gain of AR function and accelerated tumor growth under normal, as well as under castrate conditions." (PMID 25883222, 2015). "In contrast, the AR mRNA levels were not correlated with tumor grade, hormone refractoriness, or metastasis (data not shown)." (PMID 26246472, 2015).
tumor (continued). "Due to the nearly homogeneous AR expression in PSA+ PCa cells, primary HPCa and AD xenografts respond well to antiandrogens, leading to prominent reduction in tumor burden." (PMID 26246472, 2015). "In conclusion, this study provides preclinical proof-of-concept that the combination of a PI3K/mTOR inhibitor with an AR inhibitor results in a synergistic anti-tumor response in non-CRPC and CRPC models." (PMID 26506516, 2015). "Part of tumor cells expressed androgen receptor, but they were negative to CK20, CK5/6, p63 and S-100." (PMID 26055980, 2015). "This loss of AR transactivation was associated with significant increase in tumor cell death in combination treatment, indicating AR inhibition alone with AUY922 was not enough of a catalyst to induce tumor cell death." (PMID 25072314, 2014). "In summary, our preclinical data support the initiation of clinical studies evaluating enzalutamide for treatment of AR + tumors regardless of ER status, since enzalutamide uniquely blocks both androgen-mediated and estrogen-mediated tumor growth." (PMID 24451109, 2014). "In agreement with clinical observations and the role of AP-4 downregulation, our preliminary data showed that LNCaPRANKL cells overexpressing AR did have enhanced growth when inoculated as subcutaneous tumor xenografts in mice (data not shown)." (PMID 25200184, 2014). "This preclinical study supports the initiation of clinical studies evaluating enzalutamide for treatment of AR+ tumors regardless of ER status, since it blocks both androgen- and estrogen- mediated tumor growth." (PMID 24451109, 2014). "The absence of AR expression suggests that PCa CSCs are the most androgen-resistant cell type within the tumor." (PMID 24990514, 2014). "Finally from these disease modules we identify their upstream transcription factors E2F4, AR and ETS1 as potential key regulators in tumour progression." (PMID 24523864, 2014). "Prevalence of AR-positive cases was lower in high grade tumors (p<0.01), but was consistently distributed among the different tumor stages; 98.4% (300/305) of AR positive cases (98.6% in non-TNBC and 97.8% in TNBC) showed ≥10% AR expression." (PMID 24505496, 2014). "NCOA2 functions as a driver oncogene in primary tumors by increasing AR signaling; in contrast, AR amplification is largely restricted to mCRPC and likely a mechanism of drug resistance rather than a natural step in tumor progression." (PMID 25520915, 2014). "Enzalutamide very effectively blocks DHT-mediated protection against apoptosis in both ER + and ER– tumors, but it inhibits proliferation but does not affect apoptosis when opposing E2-stimulated tumor growth in ER+/AR + models." (PMID 24451109, 2014). "As a consequence, AR is reactivated in CRPC although the tumor is no longer responsive to androgen deprivation therapy." (PMID 25375370, 2014). "Those authors also reported an interaction between AR-IR and ErbB2-IR with respect to the tumour stage, but not the Gleason score." (PMID 25215939, 2014). "Since elevated cell death may also contribute to impaired tumor growth, we determined whether CAMK2N1 induces apoptosis through AR by Annexin V staining assays." (PMID 25296973, 2014). "In contrast to all other cell models the AR-negative, malignant tumour cell line PC-3 treated with AA does not show any significant effects on CYP17A1 and AKR1C3 expression." (PMID 25332874, 2014). "Tumoral BNIP3 and stromal BNIP3 were highest in the AR-positive and HER-2-negative group." (PMID 25140630, 2014). "However, the AR usually increases proliferation of PCa cell lines and receptor inhibition results in repression of CRPC tumour growth." (PMID 24895212, 2014). "It was found that 43%, 25% and 32% of HGSOC expressed high levels of AR (≥50% of tumour cells), low levels of AR (<50% of tumour cells) or no AR, respectively." (PMID 25608477, 2014).